PDCD1 (programmed cell death 1)
Diseases named in the same sentence as PDCD1 in open-access papers (continued):
Sharing a sentence is not in itself a finding about the gene and the disease.
tumor (continued). "Subclusters with Entpd1 expression were assigned as tumor-specific T cells, including Treg (CD4+Foxp3+), CD8+ effector (Gzmb+Prf1+Ifng+), CD8+ effector memory (Cd44+Cd69+), CD8+ exhausted subclusters (Pdcd1+Lag3+Tigit+Havcr2+)." (PMID 36209176, 2022). "PDCD1 exhibited high expression in exhausted CD8+ T cells (CD8-C4), and suppressive tumor Tregs highly expressed CTLA4." (PMID 34793335, 2022). "Since tumor cell–intrinsic PRC2 loss drives an immune-desert TME, we speculated that PRC2 loss might confer primary resistance to FDA-approved ICB immunotherapies, including anti–programmed cell death 1 (anti–PD-1) and anti–cytotoxic T lymphocyte–associated protein 4 (anti-CTLA4) antibodies." (PMID 35852856, 2022). "Important immunological checkpoints involved in tumor immune escape include CD274, IL1B, IL1A, PDCD1, PDCD1LG2, and SIRPA." (PMID 35401746, 2022). "The interaction of PDCD1/CD274 (PD‐L1) on the cell surface promotes T cell tolerance, minimizes autoimmune‐mediated inflammation, but also mediates the immune escape of tumour cells." (PMID 35802807, 2022). "CTLA4, HAVCR2, PVRL2, PDCD1, SIGLEC15, TIGIT, and VTCN1 expression levels were higher in tumor tissues, while CD244, LAG3, PDCD1LG2, and CD274 expression levels were found to be lower." (PMID 35923695, 2022). "Expressions of CD274, CTLA4, LAG3, PDCD1, PDCD1LG2, and SIGLEC15 were shown to be significantly different between normal and tumor samples in immune checkpoint analysis." (PMID 36588699, 2022). "COL4A1 expression was also significantly correlated with the expression levels of T cell exhaustion marker genes such as PDCD1, CTLA4, LAG3, and HAVCR2 in all the four tumor types with only two exceptions (CTLA4 in SKCM and LAG3 in STAD)." (PMID 35455650, 2022). "On the other hand, oral supplementation of non-responder patients with A. muciniphila upon FMT restored the anti-PDCD1 efficacy via IL12 by increasing the recruitment and infiltration of CXCR3+, CCR9+, CD4+ T cells into the mouse tumor site." (PMID 35463305, 2022). "SIGLEC15, PDCD1LG2(PD-L2), TIGIT, PDCD1(PD-1), CD274(PD-L1), CTLA4, LAG3, and HAVCR2(TIM3) are transcripts related to immunological checkpoints that perform vital functions in tumor immune evasion." (PMID 36253777, 2022). "Programmed cell death-1 (PD-1, also called CD279)/programmed death-ligand 1 (PD-L1, also known as CD274) is a pair of critical immune checkpoints (IC) and tumor cells can inhibit the killing effect of the immune system by activating the PD-1/PD-L1 axis." (PMID 35223466, 2022). "Biomarkers of T cell–inflamed tumor microenvironment mainly include tumor inflammation signature (TIS) and the expression of multiple inhibitory receptors (IR), including PDCD1." (PMID 36245985, 2022). "Consistently, we observed a more distinct immune phenotype at S2 tumours with reduced GZMB (granzyme B) and enriched PDCD1 (PD-1), FOXP3 and CTLA4 compared to N or S1 and S3 tumours." (PMID 35301339, 2022). "The results showed that CTLA4, HAVCR2, PDCD1, PDCD1LG2, and TIGIT significantly differed in tumor tissues and normal tissues." (PMID 36618928, 2022). "We also found DC-STAMP expression had a correlation with PDCD1, CD274, CTLA-4, and TIGIT which were exhaustion markers of T cells and considered a dysfunction of anti-tumor immunity." (PMID 35571050, 2022). "The expression of CD274, CTLA4, LAG3, PDCD1, PDCD1LG2 and SIGLEC15 was significantly different between adjacent normal tissues and tumor tissues." (PMID 36588699, 2022). "Immunotherapy, as a tumor therapy, had been validated in a variety of tumors, among which CTLA4 and PDCD1 were the most studied." (PMID 35126519, 2022). "In the human Pdcd1 transgenic mice, the B16F10 tumour cell was sensitive to pembrolizumab treatment." (PMID 36077671, 2022). "Immune checkpoint blockade (ICB), such as anti-programmed cell death-1 (α-PD1) therapy, has achieved remarkable success to fight cancer in the clinic, with moderate responses occurring in immunogenic (hot) tumor model." (PMID 35812418, 2022).
tumor (continued). "Translational research (including evaluation of tumor microenvironment, oncogenic TCR alterations, and Pdcd1 genomic deletions) will also be performed to identify predictive markers of efficacy." (PMID 35028526, 2022). "Tumor-associated double positive expanded clonotypes frequently displayed a Tem phenotype and expressed elevated exhaustion markers PDCD1, TIM3, LAG3 and CTLA4 similar to tumor-restricted CD8+ expanded clonotypes." (PMID 36185254, 2022). "In the HCC tumor microenvironment, PDCD1 is expressed in CD8+ T cells, and when activated, PDCD1 inhibits T cell migration, proliferation and secretion of cytotoxic mediators, thereby blocking the “cancer immune cycle”." (PMID 34869039, 2021). "Exhausted (terminal differentiation) CD8+ T cells (cluster 10 in Paratumor and cluster 0 in Tumor) were enriched with exhaustion genes CTLA4, PDCD1 and HAVCR2." (PMID 33429363, 2021). "Systemic treatment with immune checkpoint inhibition (ICI) targeting programmed cell death 1 (anti-PD-1) and cytotoxic T-lymphocyte antigen-4 (anti-CTLA-4) can overcome tumor-induced immunosuppression in advanced malignancies." (PMID 34572865, 2021). "DUSP12 expression was positively correlated with the abundance of tumor-infiltrating CD4+ T cells, macrophages, neutrophils, dendritic cells, and expression of the immune-checkpoint moieties HARVC2, TIGIT, CTLA4 and PDCD1." (PMID 34414037, 2021). "Each CD44+ cell-type functions immunosuppression through different ways: CD44+ tumor cells express CD276, IL13, VEGFA, and IDO1; CD44+ TAMs express IL10, TGFB1, VEGFA, and HAVCR2; CD44+ T cells express CD274, TGFB1, CTLA4, LAG3, and PDCD1." (PMID 35187044, 2021). "To investigate the dynamic changes of PDCD1 and HAVCR2 on Treg cells in tumor progression, we analyzed the gene expression on tumor-infiltrated Treg cells in TCGA datasets." (PMID 33936081, 2021). "In this way, PDCD1 regulatory elements control the secretion of IL12P70, which will only be expressed with the CAR T cells encountering the tumor antigen." (PMID 35008348, 2021). "With increased tumor PD-L1, the expression of inhibitory checkpoint molecules (ICMs), including ADORA2A, BTLA, CD160, and PDCD1, was downregulated while the expression of IDO1 was upregulated." (PMID 33754038, 2021). "The emerging biomarkers for ICI efficacy include, principally, (i) programmed cell death-1 (PD1), (ii) its ligand-1 (PD-L1) and (iii) high levels of tumor-infiltrating lymphocytes (TILs)." (PMID 33670162, 2021). "For CD8+ T cells, although the cytotoxic molecules (GZMA, GZMB, NKG7, and PRF1) were highly expressed, a fraction of CD8+ T cells showed positive with exhaustion biomarkers (CTLA4, PDCD‐1, and TIGIT), indicating their tumor‐cytotoxic activity was constrained." (PMID 34185421, 2021). "PD-1 (PDCD-1) and CTLA-4 are important immune checkpoints that are responsible for tumor immune escape." (PMID 34754620, 2021). "Several marker genes, FOXP3, STAT3, PDCD1, TGFB1, IL10, HMGB1, which are significantly related to the tumor microenvironment induced by radiation, had significant functional differences in the distribution of CD8+T cells clusters." (PMID 33968889, 2021). "Programmed cell death 1 (PD-1, also known as PDCD1) on the surface of CD8+ T cells binds to programmed cell death ligand 1 (PD-L1, also known as CD274) produced by tumor tissue, leading to a limited host immune response." (PMID 33465047, 2021). "Sarcoma data from the TCGA were downloaded to analyze the lncRNAs positively correlated with immune checkpoint inhibitory molecules (CD274, CD80, CD86, PDCD1 LG2 and LGALS9), which accelerate the process of tumor cell immune evasion." (PMID 34178688, 2021). "In recent years, immune checkpoint inhibitors blocking programmed cell death 1 and its ligand (PD-1/PD-L1) and cytotoxic T-lymphocyte antigen-4 (CTLA-4) have shown promising preliminary results in various kinds of tumours." (PMID 33632199, 2021).
tumor (continued). "MicroRNA miR-138 was suggested to function as a tumour suppressor and has been shown to target CTLA-4 and programmed cell death 1 (PD-1) in CD4+T cells." (PMID 32054041, 2020). "In addition to the expression of CTLA-4 and PDCD1, tumor-infiltrating lymphocytes (TILs) express a number of other co-inhibitory receptors, including HAVCR2 and TIGIT, providing additional targets that could be exploited for inducing anti-tumor immune responses." (PMID 33585210, 2020). "In HCC, we observed increased expression of several more activation- (IFNG, CD38, IL2RA, TNFRSF9) and exhaustion-related (TIGIT, CTLA4, PDCD1, ENTPD1) genes in tumor MAIT cells." (PMID 32849590, 2020). "Programmed cell death 1 (PD‐1), programmed death ligand‐1 (PD‐L1) and Cytotoxic T‐lymphocyte‐associated protein‐4 (CTLA‐4) could inhibit the proliferation and differentiation of immunocompetent cells and the recognition of tumour cells by tumour‐infiltrating lymphocytes (TILs)." (PMID 33145941, 2020). "Compared with other immunotherapy, programmed cell death 1 (PD-1) and its ligand, PD1 ligand 1 (PD-L1) demonstrated a good effect on durable tumor regression and stabilization of disease." (PMID 32457618, 2020). "The neutrophil–lymphocyte ratio (NLR) is of great significance in patients subject to immunotherapy (Programmed cell death 1 (PD-1)/PDL-1) and correlates with tumor progression." (PMID 32722054, 2020). "To identify regulatory factors promoting T cell exhaustion in the tumor microenvironment, we prioritized TFs by differential expression between two subsets of TI CD8+ T cells divided by different levels of PDCD1 expression." (PMID 32111241, 2020). "The PDCD1/CD247 axis plays a pivotal role in the effector function of T-cells, i.e., in T-cells residing within (tumor) tissue." (PMID 33240813, 2020). "These CD8-LAYN cells in HCC have highly expressed exhaustion markers such as CTLA-4, PDCD1, and HAVCR2, suggesting that they are exhausted cells by tumor-antigen stimulation." (PMID 33379384, 2020). "We indirectly determined the efficiency of IL-12P70 matrix insertion at the IL2rα or PDCD1 loci by assessing the expression of ΔLNGFR at the surface of TRACCAR T cells and characterizing IL-12P70 secretion upon tumor cell engagement." (PMID 31723132, 2019). "Programmed cell death ligand 1 (PD-L1) interacts with Programmed cell death 1 (PD1) on effector T cells, NK cells and TAMs inhibiting their anti-tumor activity." (PMID 31681563, 2019). "As a proof of concept, we simultaneously repurposed TRAC along with the IL2rα or PDCD1 genes to express a CAR at the surface of primary T cells and to harness T cell engagement with tumor cell targets to promote conditional and transient secretion of IL-12P70." (PMID 31723132, 2019). "Intriguingly, tumor-reactive markers (CD39 and CD103) and exhaustion markers (PDCD1, LAYN, and HAVCR2) were specifically demethylated." (PMID 31892342, 2019). "Targeted immune checkpoints are the programmed cell death 1 (PD-1) and the cytotoxic T lymphocyte antigen 4 (CTLA-4), both expressed on T cells, while PD-L1 is produced by tumor cells." (PMID 31877735, 2019). "We then injected equal numbers of vehicle or G-1 treated tumor cells into syngeneic C57BL/6 mice, and treated the animals with either anti-programmed cell death 1 (αPD-1) antibody or isotype antibody control." (PMID 29336307, 2018). "Several recent examples have demonstrated the potential for various types of oncolytic viruses expressing immune checkpoint inhibitors such as anti-PDCD1 (PD-1), anti-CD274 (PD-L1), and anti-CTLA4, as well as other anti-tumor antibodies." (PMID 28822103, 2018). "Programmed cell death 1 (PD-1; CD279) is an inhibitory receptor expressed by tumor-infiltrating lymphocytes (TILs), such as activated T cells, B cells, and natural killer (NK) cells." (PMID 30733677, 2018).
tumor (continued). "Programmed cell death-1 (PDCD1/PD-1) and its ligand programmed cell death 1 ligand 1 (CD274/PD-L1) have been reported to suppress anti-tumor T cell-mediated immune responses." (PMID 30353144, 2018). "Programmed cell death 1 (PD-1; also known as CD279) is expressed in several cell types including T-lymphocytes, specifically CD8 tumor-infiltrating lymphocytes, which are in charge of directly eradicating tumor cells." (PMID 29562664, 2018). "The immune checkpoint proteins programmed cell death 1 (PDCD-1/PD-1) and programmed cell death-ligand 1 (CD274/PD-L1) are expressed on both tumor cells and immune cells." (PMID 30353144, 2018). "We found that Eomes bound to the promoter and −23.8 kb enhancer of Pdcd1, which were accessible only in exhausted CD8+ T cells in tumor or during chronic viral infection." (PMID 30619337, 2018). "Immune checkpoint blockade therapies (ICBTs) targeting programmed cell death 1 (PD-1) and its ligand programmed death ligand-1 (PD-L1/B7-H1/CD274) have exhibited momentous clinical benefits and durable responses in multiple tumor types." (PMID 29910728, 2018). "Other metabolites produced by specific species of microbes can modify the activity of therapeutic agents, including PD-1 (PDCD1)/PD-L1 (CD274) targeting immunotherapies, in melanomas and other tumor types." (PMID 29945886, 2018). "In addition, pembrolizumab, an anti-programmed cell death-1 (PD-1) antibody, was shown to be superior to combined therapy with a platinum agent as first-line treatment for diseases with more than 50% programmed cell death ligand 1 (PD-L1) expression in a tumor surface." (PMID 29854794, 2018). "The expression level of CTLA4 only correlated with central tendency parameters, while expression of GLUL, FGFR4, tumour stemness markers KRT19 and EPCAM and immune checkpoint PDCD1 showed significant correlations with MRI heterogeneity parameters only." (PMID 28550313, 2017). "Programmed cell death-1 (PD-1), an immunoinhibitory receptor of the CD28 family, which plays a major role in tumor immune escape, is an inhibitory receptor expressed on the surface of T cells that physiologically limits T-cell activation and proliferation." (PMID 28423711, 2017). "Significant differences in the CpG-methylation patterns between tumor tissues and matched controls were observed for CTLA4 and PDCD1 (PD1) showing a decreased methylation of these genes compared to matched tumor-free tissues from the same patients." (PMID 28503213, 2017). "GITR is similar to programmed cell death-1 (PD-1) and cytotoxic T-lymphocyte antigen 4 (CTLA-4), both of which have been applied clinically as immune modifiers in tumor therapy." (PMID 25105508, 2014). "The expression of several lymphocyte signaling molecules, including CTLA4, LAT, PDCD1, and ZAP70, was maintained in the transition from human tumor to CX, and was particularly prominent in the CXs derived from D61540." (PMID 24278200, 2013). "PVR/TIGIT, NECTIN2/CD226, and FAM3C/PDCD1 were relatively more strongly expressed in Plac1+ epi‐CD4+ T cells than Plac1− epi‐CD4+ T cells and PVR was specific for Plac1+ tumor cells, which was subsequently validated in HNSCC cells in vitro and in the TMA cohort by mIF." (PMID 40056047, 2025). "Interestingly, while succinylation levels were elevated in tumor-proximal immune cells, overall succinylation scores in CRC showed a negative correlation with the expression of immune checkpoint molecules such as PDCD1 (PD-1), CD274 (PD-L1), and CTLA4." (PMID 40463370, 2025). "Interestingly, METTL14-mediated m6A-dependent degradation of PDCD1 mRNA reduces PD-1 expression, maintaining CD8+ T-cell activation and restraining tumor growth." (PMID 41164187, 2025). "Corroborating this observation is the fact that tumor-intrinsic RB activation resulted in no overt changes to Pdcd1 or Ctla4 and even a potential reduction in PD-L1, which would suggest that approaches designed around those targets would prove inconsequential." (PMID 41326426, 2025).
tumor (continued). "Moreover, in the healthy donor samples, it showed markedly lower expression of TIGIT, PDCD1, and CXCL13, indicating that this specific co-expression pattern is tumor-specific." (PMID 40799645, 2025). "ALK was upregulated in a subset of tumors, particularly in non-smokers, while PDCD1 was predominantly expressed in immune-rich tumor microenvironments." (PMID 40927719, 2025). "Also, while not differentially expressed, the important immune checkpoints PDCD1 (PD1) and CTLA4 were present in all tumor samples." (PMID 40149290, 2025). "Notably, several of these checkpoints (e.g., PDCD1, LAG3, TIGIT and CTLA4) collectively impair T cell function through distinct mechanisms, driving immune evasion and tumor progression." (PMID 41562077, 2025). "Subsequently, all factors identified from the univariate analysis were included in the multivariate analysis: age, PDCD1/CD27 ratio, PDCD1/TNFSF4 ratio, IDO1/TMIGD2 ratio, IDO1/TNFSF4 ratio, neoadjuvant treatment, initial weight of tumor, ER status, PR status, HER2 status, and TNM stage." (PMID 40061889, 2025). "Furthermore, spatially exclusive relationships between LRFN2+ tumor cells and CD8+ T cells, as well as markers such as programmed cell death-1 (PD-1) and T cell factor 1 (TCF-1), have been observed, thereby enhancing tumor resistance." (PMID 40438606, 2025). "Furthermore, immune checkpoint analysis revealed that ALDOA-high tumors exhibit reduced expression of key immune checkpoints, including PDCD1, CTLA4, and TIGIT, potentially reducing immune cell engagement with the tumor and further promoting immune evasion." (PMID 41239433, 2025). "In liver hepatocellular carcinoma (LIHC), the positive correlation between LRFN4 and immunotherapy targets such as PDCD1 and CTLA4 implies that LRFN4 can impact the interaction between immune cells and tumor cells, potentially modulating the efficacy of immune checkpoint blockade (ICB) therapy." (PMID 40386777, 2025). "The NanoString tumor panel detected in treatment-naïve tumors of the L-TTF2 group higher immune infiltration (e.g., cytotoxic T-cells, B-cells) and checkpoint markers (e.g., PDCD1, CTLA4, TIGIT)." (PMID 40696453, 2025). "The CellphoneDB analysis of ligand-receptor pairs showed that the interaction networks between UPP1high tumor cells and FOXP3+ Tregs/LAG3 + PDCD1 + CD8 + T cells were involved with numerous immune checkpoints, including CD274/PDCD1LG2_PDCD1, FGL1_LAG3, and NECTIN_TIGIT." (PMID 38331898, 2024). "Importantly, by surveying public databases, we observed significant positive correlations between PDCD1 and TGFB1 gene expression in most human tumor types." (PMID 38441961, 2024). "As a first approach, we tested whether PDCD1 and LAG3 gene expression in tumor-immune infiltrate estimates correlated with immune cell infiltration by lymphoid (Fig. EV1A) and myeloid (Fig. EV1B) lineages." (PMID 39030301, 2024). "Immunophenotyping serine-deprived CT26 tumors revealed that tumor-infiltrating CD8+ T cells exhibit multiple markers of terminal dysfunction, notably programmed cell death 1 (PDCD1, best known as PD-1), pointing to the possibility of harnessing a PD-1 blocker to further increase disease control." (PMID 39206097, 2024). "Tumor-specific CD8 + T cells exhibited higher expression levels of cytotoxicity-related genes IFNG and GZMK, immune regulators FOS and JUN, and exhaustion markers TIGIT and PDCD1." (PMID 39033098, 2024). "Immunofluorescence staining also showed that the JAK‐STAT1 pathway was activated (high STAT4+) in tumour‐infiltrating T cells, whereas the PDCD1+ ratio was not significantly different." (PMID 39658531, 2024). "In this study, the expression of FAM110B was positively correlated with various immune checkpoints such as PDCD1, CTLA4, EDNRB, TLR4, etc., indicating that FAM110B may be a new target for tumor immunotherapy." (PMID 39170745, 2024).